GHITM (growth hormone inducible transmembrane protein)
Description:
Plays an important role in maintenance of mitochondrial morphology and in mediating either calcium or potassium/proton antiport. Mediates proton-dependent calcium efflux from mitochondrion. Also functions as an electroneutral mitochondrial proton/potassium exchanger. Required for the mitochondrial tubular network and cristae organization. Involved in apoptotic release of cytochrome c. Inhibits the proteolytic activity of AFG3L2, stimulating respiration and stabilizing respiratory enzymes in actively respiring mitochondria. However, when mitochondria become hyperpolarized, GHITM loses its inhibitory activity toward AFG3L2 and the now the active AFG3L2 turns first on GHITM and, if hyperpolarization persists, on other proteins of the mitochondria, leading to a broad remodeling of the mitochondrial proteome.
Synonyms: MICS1; DERP2; TMBIM5; My021; HSPC282; PTD010
Tractability: Antibody: UniProt predicts a signal peptide or a membrane-spanning region. PROTAC: ubiquitination databases record sites on it; its protein half-life has been measured.
Gene: Protein-coding gene on chromosome 10 (84,139,482 to 84,154,841, forward strand). Ensembl gene ENSG00000165678.
Subcellular location: Mitochondrion inner membrane
Subcellular location (Human Protein Atlas): Mitochondria
Gene Ontology:
Molecular function: calcium:proton antiporter activity; potassium:proton antiporter activity; protein binding; calcium channel activity
Biological process: calcium export from the mitochondrion; calcium ion transport; inner mitochondrial membrane organization; mitochondrial calcium ion transmembrane transport; negative regulation of release of cytochrome c from mitochondria; positive regulation of mitochondrial ATP synthesis coupled electron transport; mitochondrial potassium ion transmembrane transport; proton transmembrane transport
Cellular component: endoplasmic reticulum membrane; extracellular exosome; mitochondrial inner membrane; mitochondrial membrane; mitochondrion
Genetic constraint (gnomAD): Loss-of-function variants: 2 observed, 6.52 expected, observed/expected ratio (o/e) 0.31, 90% interval 0.12 to 0.96. That is too few expected variants to judge how well the gene tolerates losing a copy. Missense variants: 141 observed, 156.19 expected, observed/expected ratio (o/e) 0.9, 90% interval 0.79 to 1.04. Synonymous variants: 64 observed, 62.04 expected, observed/expected ratio (o/e) 1.03, 90% interval 0.84 to 1.27.
Homologues: Orthologues: chimpanzee GHITM (99% identical), macaque GHITM (97% identical), pig GHITM (94% identical), dog GHITM (92% identical), mouse Ghitm (92% identical), rat Ghitm (90% identical), guinea pig GHITM (85% identical), tropical clawed frog ghitm (75% identical), Caenorhabditis elegans K11H12.8 (49% identical), Drosophila melanogaster CG2076 (48% identical), Drosophila melanogaster Mics1 (48% identical). Paralogues in human: TMBIM6 (16% identical), GRINA (16% identical), FAIM2 (16% identical), TMBIM1 (14% identical), TMBIM4 (13% identical).
Diseases named in the same sentence as GHITM in open-access papers:
GHITM is named in the same sentence as 20 diseases in open-access papers, as found by Europe PMC text mining. Sharing a sentence is not in itself a finding about the gene and the disease. The quoted sentences say what the papers report.
renal carcinoma (3 papers, 2020 to 2025). A carcinoma arising from the epithelium of the renal parenchyma or the renal pelvis. "Our study showed that ectopic overexpression of GHITM could enhance the sensitivity of renal cancer cells to sunitinib and the antitumor effects of PD‐1 blockade, which was consistent with previous bioinformatics analysis." (PMID 38588015, 2024). "GHITM (also known as TMBIM5), another proposed Ca2+/H+ antiporter, is similarly downregulated in renal cancer, and its overexpression inhibited proliferation and migration in a cell line model." (PMID 40985275, 2025). "Taken together, our study revealed that GHITM was a promising therapeutic target for KIRC, which could modulate malignant phenotype and sensitivity to PD‐1 blockade of renal cancer cells via Notch signalling pathway." (PMID 38588015, 2024).
glioma (1 paper, 2024). A benign or malignant brain and spinal cord tumor that arises from glial cells (astrocytes, oligodendrocytes, ependymal cells). "Correlation analysis revealed that TSPAN4 was positively correlated with ITGB1, GDF15, ITGA3 and ITGA6, and negatively correlated with CHD7, ASPDH, TMEM8B and GHITM in glioma." (PMID 39723210, 2024).
Insulin resistance (1 paper, 2022). Increased resistance towards insulin, that is, diminished effectiveness of insulin in reducing blood glucose levels. "Decreased GHITM expression and loss of cristae organisation occur at an early stage of DIO and represent an IRF5-dependent mechanism that may contribute to loss of microenvironmental homeostasis and development of insulin resistance." (PMID 36042203, 2022).
Obesity (1 paper, 2022). Accumulation of substantial excess body fat. "Here authors show that IRF5 transcriptionally represses the Growth Hormone Inducible Transmembrane Protein gene encoding a mitochondrial protein important for oxidative respiration in macrophages, thus driving the detrimental metabolic changes observed in obesity." (PMID 36042203, 2022).
Parkinson disease (1 paper, 2020). A progressive degenerative disorder of the central nervous system characterized by loss of dopamine producing neurons in the substantia nigra and the presence of Lewy bodies in the substantia nigra and locus coeruleus. "The only member with a mitochondrial localization is TMBIM5 (also known as GHITM or MICS1), which affects cristae organization and associates with the Parkinson’s disease-associated protein CHCHD2 in the inner mitochondrial membrane." (PMID 32977469, 2020).
cancer (3 papers, 2019 to 2024). A tumor composed of atypical neoplastic, often pleomorphic cells that invade other tissues. "The infiltration level of cancer associated fibroblast cells, the protumor immune cells, was negatively associated with GHITM levels (r = −0.264, p = 8.17e‐9)." (PMID 38588015, 2024). "Little study is conducted to explore the biological role of GHITM in cancer, a majority of current research focuses on its effect on mitochondrial function." (PMID 38588015, 2024). "Few studies have been conducted recently on expression pattern and prognostic significance of GHITM in cancer." (PMID 38588015, 2024). "Moreover, we explored the association between GHITM expression of TCGA‐KIRC patients and their sensitivity to chemotherapeutic agents which were validated to be effective in other kinds of cancer." (PMID 38588015, 2024). "Exploration of LinkedOmics database and GSEA of the GSE126964 dataset prompted us GHITM may play its significance in cancer by regulating Notch signalling pathway." (PMID 38588015, 2024). "Our findings elucidated GHITM could be an important regulator in cancer cells immunity and a new target for immunotherapy." (PMID 38588015, 2024). "GHITM was downregulated in all variables in TCGA‐KIRC samples, including patient age, gender, stage of cancer and tumour grade, compared to normal." (PMID 38588015, 2024). "Based on these results, we propose that targeting the YY1/GHITM/Notch1 axis could decrease the malignant behaviour of KIRC cells and potentiate antitumour efficacy of cancer therapy, which provides a promising and novel therapeutic strategy for KIRC patients." (PMID 38588015, 2024).
tumor (2 papers, 2024 to 2025). "TCGA samples and GEO series exhibited that compared with normal tissues, KIRC tumour tissues had a lower level of GHITM." (PMID 38588015, 2024). "Additionally, GHITM downregulation correlated closely with tumour stage and tumour grade in TCGA‐KIRC cohort, lower GHITM expression was observed in advanced KIRC." (PMID 38588015, 2024). "However, up until now, the expression pattern and biological function of GHITM in tumour progression has not yet been reported." (PMID 38588015, 2024).
GHITM also shares sentences with these, for which no sentence is quoted: allergic disease (6 papers); asthma (4); Allergy (2); Skeletal myopathy (2); allergic rhinitis (1); bacterial infection (1); head and neck cancer (1); inflammation (1); keratoconus (1); Neurological Disorder (1); pancreatic adenocarcinoma (1); respiratory allergic diseases (1); type-2 diabetes (1).